TSHR (thyroid stimulating hormone receptor)
Diseases named in the same sentence as TSHR in open-access papers (continued):
Sharing a sentence is not in itself a finding about the gene and the disease.
Graves disease (continued). "The use of fibroblasts that express both TSHR and also MHC class II molecules was based on the observation of aberrant expression of MHC class II molecules on thyrocytes from patients with autoimmune thyroid diseases (AITD), including Graves’ disease." (PMID 27895620, 2016). "On the other hand, the specific detection of TSAbs without interference of other antibodies directed against TSHR makes the Mc4 assay potentially useful in the follow-up of patients with Graves’ disease." (PMID 27504107, 2016). "To determine if the TSHR-Glo assay was useful in measuring stimulating antibodies in patients with Graves’ disease, we used sera with known TSHR antibodies and control sera that were negative." (PMID 26858688, 2016). "In Graves’ disease, although TSH is markedly suppressed, the TSHR antibodies present in the patients’ sera, thus it could stimulate the TSH signaling of cells." (PMID 26650844, 2015). "Here we report an usual case of coexisting Graves’ disease with functioning struma ovarii and the TSHR staining result, including the TSHR staining of the patient with non-functioning struma ovarii." (PMID 26530865, 2015). "Human autoimmune thyroid disease (AITD) is an organ-specific immune disease characterized by autoantibodies, such as anti-thyroglobulin (Tg) antibody, anti-thyroperoxidase (TPO) antibody and anti-TSH receptor (TSHR) antibody, mainly involving Hashimoto’s thyroiditis (HT) and Graves’ disease (GD)." (PMID 25429429, 2014). "Autoantibodies to thyrotropin receptor (TSHR) in Graves' disease do not efficiently bind to the TSHR recombinant produced in an in vitro TnT system." (PMID 24416061, 2013). "Currently, the assays available to detect TSHR-Abs in patients with Grave's disease reach a sensitivity of ~80% but with a specificity of 100% TSHR-Abs are not found in any disease other than AITD." (PMID 23691429, 2013). "TSHR autoantibodies with either stimulatory (TSAb) or blocking (TBAb) activity are a key feature of autoimmune thyroid disease (AITD), with TSAb having a pre-dominant effect in Graves' disease (GD) leading to hyperthyroidism." (PMID 21124799, 2010). "TSHr stimulation increased in vitro SOD release and the 4-HNE, which was confirmed by the in vivo measurements showing higher oxidative stress markers, such as malondialdehyde, 8-isoprostane and 8-hydroxy-2-deoxy guanosine in the urine of patients with untreated Graves’ disease." (PMID 32973319, 2020). "TSHR antibodies (TRAbs) in serum from Graves’ disease patients can now be clinically evaluated by non-radioactive third generation assay, in which the autoantibodies inhibit binding of a biotin-labeled human monoclonal thyroid-stimulating antibody M22 to TSHR-coated ELISA plate wells." (PMID 27895620, 2016). "In conclusion, the activation of TSHR antibody-activated TSH signaling contributes to high bone turnover, independent of the actions of thyroid hormone, and thyroid-stimulation blocking antibody has protective effects against bone metabolism in Graves’ disease." (PMID 26650844, 2015). "In conclusion, our results suggest that the activation of TSHR antibody-activated TSH signaling contributes to high bone turnover, independent of the actions of the thyroid hormone, and thyroid-stimulation blocking antibody has protective effects on bone metabolism in Graves’ disease." (PMID 26650844, 2015). "We show that it is not possible to detect the blocking variety of TSHR antibody in patients with Graves’ disease because the stimulating antibody may overwhelm the measurement of blocking in the bioassays available for their measurement and may blind the valid interpretation of the results." (PMID 35909553, 2022). "The levels of Anti-TSHR, Anti-TPO, and Anti-TG were within normal limits, effectively excluding a diagnosis of Graves’ disease and suggesting the absence of significant inflammatory destruction of thyroid tissue at this juncture." (PMID 40726736, 2025).
Graves disease (continued). "In humans with Grave's disease, the BAFF levels significantly correlated with Tg-Ab but not with TPO-Ab nor TSHR-Ab." (PMID 23691429, 2013).
hyperthyroidism (324 papers, 2005 to 2026). Overactivity of the thyroid gland resulting in overproduction of thyroid hormone and increased metabolic rate. "While a majority of GD patients suffer from hyperthyroidism as caused by stimulating anti-TSHR Abs, a smaller subset of patients can exhibit hypothyroidism when their primary autoantibodies are blocking anti-TSHR Abs that prevent normal binding of TSH." (PMID 40264771, 2025). "In GD, hyperthyroidism is caused by autoantibodies targeting the thyroid stimulating hormone receptor (TSHR), which act as agonists to stimulate excessive thyroid hormone production." (PMID 40416990, 2025). "Hyperthyroidism was induced in female BALB/c mice by three intramuscular injections of adenovirus-encoding human TSH receptor (Ad-TSHR)." (PMID 41010493, 2025). "Since stimulation of the TSHR is the primary cause of hyperthyroidism, various research teams have been working on methods to block TSHR signaling, either by employing small chemicals or antibodies which prevent receptor activation." (PMID 38161204, 2024). "The present case cannot be attributed to a hereditary variant of the disease owing to the lack of a family history of thyroid diseases and the fact that in 2015, an increase in TSHR-Ab levels associated with pronounced hyperthyroidism was observed." (PMID 38813368, 2024). "Here, we report a patient of inactivation mutation in TSHR gene complicated with hyperthyroidism, which improve clinicians’ understanding of TSHR gene mutation and provide diagnosis experience." (PMID 38241561, 2024). "In contrast, pathologically elevated serum TSH levels, TSHR-stimulating antibodies, or constitutively active TSHR mutations stimulate thyroid hormone production and thyroid growth, resulting in hyperthyroidism and goiter." (PMID 38194289, 2024). "These autoantibodies, known as TSHR autoantibodies (TRAb), bind to and stimulate the TSHR, causing excessive thyroid hormone production and the clinical manifestations of hyperthyroidism." (PMID 39735549, 2024). "Possible mechanisms of hyperthyroidism in patients with thyroid carcinoma include somatic mutations in the gene for thyrotropin receptor (TSHR) or mutations in the PRKAR1A gene." (PMID 39049862, 2024). "In conclusion, we have identified a TSHR inactivation missense mutation in a patient with hyperthyroidism." (PMID 38241561, 2024). "We identified the G132R monoallelic heterozygous mutation of TSHR gene in a patient with hyperthyroidism." (PMID 38241561, 2024). "This process eventually produces autoantibodies to TSHR, which stimulate thyroid cell growth and secretion, causing hyperthyroidism, goiter, as well as associated conditions such as ophthalmopathy and dermopathy." (PMID 39872521, 2024). "The upregulation of TSHR gene expression has also been reported to be potentially associated with hyperthyroidism." (PMID 39771102, 2024). "Graves’ hyperthyroidism is caused by autoantibodies to the thyroid-stimulating hormone receptor (TSHR) that act as agonists and induce excessive thyroid hormone secretion, thus releasing the thyroid gland from pituitary control." (PMID 37892693, 2023). "Hyperthyroidism in GD is caused by circulating auto-antibodies that stimulate the TSH-receptor (TSHR), leading to unregulated production and secretion of thyroid hormones." (PMID 38107298, 2023). "Most neonatal hyperthyroidism is transient, commonly caused by stimulation by maternal thyroid-stimulating hormone receptor antibody (TRAb) crossing the placenta, resulting in a baby’s high thyroid hormone secretion." (PMID 35413827, 2022). "used a plasmid that encodes TSHR for genetic immunization, which induced Graves’-like hyperthyroidism." (PMID 35813642, 2022). "Thyroid Stimulating Hormone Receptor (TSHR) controls thyroid cell metabolism, and defective TSHR causes hyperthyroidism." (PMID 36553569, 2022).
hyperthyroidism (continued). "In order to further improve the success rate of inducing hyperthyroidism, many researchers have used an adenovirus containing TSHR-289, a subunit encoded human TSHR, to induce GD." (PMID 35813642, 2022). "In contrast, GD is mainly associated with hyperthyroidism, resulting from the presence of thyroid-stimulating antibodies which activate thyrotropin receptor (TSHR) on thyrocytes, leading to thyroid hyperplasia." (PMID 34981746, 2022). "GD, which is characterized by hyperthyroidism caused by thyrotropin receptor (TSHR)-stimulating antibodies, shows an increased Th2 response (IL-4 and IL-10), and thus, increased humoral immunity." (PMID 35894054, 2022). "GD related hyperthyroidism is primarily caused by binding of TRAb to the thyrotropin receptor (TSHR) on the thyroid follicular endothelial cells, thereby stimulating the excessive secretion of the thyroid hormones." (PMID 35069441, 2021). "Graves’ hyperthyroidism is an autoimmune condition that arises as a result of the loss of immunological tolerance to the thyroid-stimulating hormone receptor (TSHR)." (PMID 32845332, 2020). "It was shown that immunization by Adenovirus-TSHR289, which encoded only the A subunit of the human TSHR-induced hyperthyroidism and TRAb to a greater extent than immunization by adenovirus carrying the full length TSHR wild type." (PMID 32399893, 2020). "In particular, hyperthyroidism due to autoimmune disease or thyroid autonomy is linked with TSHR activation via autoantibodies or mutations respectively." (PMID 32303903, 2020). "Here, stimulating TSHR abs cause hyperthyroidism and induction of a unique syndrome, which is different from sole hyperthyroidism initiated by the presence of increased peripheral hormones." (PMID 33384684, 2020). "Graves’ ophthalmopathy occurs mainly in Graves’ hyperthyroidism, which is caused by thyroid-stimulating hormone receptor-stimulating antibodies produced by lymphocytes in the thyroid gland or lymph nodes." (PMID 30547812, 2018). "Instead, TSAb and Graves’-like hyperthyroidism can be induced in mice or hamsters by injecting intact eukaryotic cells expressing the TSHR or by injecting plasmid/adenoviral vectors encoding the TSHR or, more efficiently, its A-subunit." (PMID 28620373, 2017). "Small molecule inhibitors and monoclonal TBAb target the proximate cause of hyperthyroidism, the TSHR." (PMID 28620373, 2017). "Over-activation of the cAMP pathway by chronic TSHR stimulation causes excess hormone secretion and thyroid hyperplasia, which results in clinical hyperthyroidism." (PMID 28117293, 2017). "C57BL/6 mice were less susceptible in that only 25% of the females developed hyperthyroidism after the ad-TSHR immunization." (PMID 27895620, 2016). "GD is characterized by hyperthyroidism caused by stimulatory anti-TSHR antibodies (TRAb, TSAb, TSI)." (PMID 27602020, 2016). "Mutations in TSHR can be loss of function or gain of function, leading to hypo or hyperthyroidism, respectively." (PMID 26518340, 2015). "We report here that TSH and the pathogenic anti-TSHR antibodies that drive hyperthyroidism in GD induce IL-6 expression in fibrocytes and orbital fibroblasts." (PMID 24086448, 2013). "In contrast, in GD, the lymphocytic infiltration of the thyroid leads to activation of TSH-receptor- (TSHR) reactive B cells that secrete TSHR-stimulating antibodies causing hyperthyroidism." (PMID 22242199, 2012). "Our initial goal for investigating mice of the AXBXA set was to expand our studies of the genetic basis for susceptibility to induced hyperthyroidism and TSHR antibodies." (PMID 21738647, 2011). "Of note, several ECL1 mutations that alter TSHR constitutive activity have been identified in patients with hypothyroidism (TSHR loss-of-function) or hyperthyroidism (gain-of-function) emphasizing the importance of ECL1 in in vivo settings." (PMID 21931793, 2011).
hyperthyroidism (continued). "Pre-treating BALB/c mice with TSHR A-subunit protein before A-subunit adenovirus immunization attenuated hyperthyroidism by “deviating” the humoral response from pathogenic (TBI and TSAb positive) towards TSHR-ELISA antibodies." (PMID 21738647, 2011). "Hyperthyroidism in Graves' patients is caused by autoantibodies to the thyrotropin receptor (TSHR) that mimic the stimulatory activities of the ligand (TSH) on the thyroid gland." (PMID 21738647, 2011). "In two RI families (CXB and BXH), development of TSHR antibodies was linked to loci in the MHC region whereas genes on different chromosomes were linked to hyperthyroidism." (PMID 21738647, 2011). "In this report, we present a Turkish boy with sporadic congenital hyperthyroidism who presented with severe symptoms of hyperthyroidism in early infancy and a heterozygous TSHR germline mutation." (PMID 21274318, 2010). "Our data suggests that TSHR CAAR T cells could be an effective therapy for both GD-caused hyperthyroidism and GD-caused hypothyroidism." (PMID 40264771, 2025). "Hyperthyroidism causes oxidative stress that increases innate and adaptive immune responses in patients with GD, increasing the risk of GO presentation, although hypothyroidism also increases the risk of GO presentation and exacerbation by TSHR overactivation." (PMID 38488977, 2024). "Surprisingly, strong constitutive activity of both Gαs and Gαq/11, detected in our recently developed NAH mouse model, carrying a patient-derived TSHR D633H mutation led to only relatively mild and transient hyperthyroidism but advanced to papillary thyroid carcinoma (PTC)." (PMID 38194289, 2024). "In general, familial gestational hyperthyroidism caused by TSHR CAM is rare." (PMID 38194289, 2024). "TSHR antibodies can cause hyperthyroidism, successfully producing a GD mouse model." (PMID 39456701, 2024). "However, during 4–8 weeks of sufficient-iodine (0.3 mg/kg) diet, the homozygous TSHR M453T mice developed hyperthyroidism, associated with goiter, hypertrophic thyroid follicles, and increased thyrocyte proliferation." (PMID 38194289, 2024). "Additionally, BALB/cJ mice injected with TSHR-Abs on a vitamin D-deficient diet showed higher susceptibility to sustained hyperthyroidism compared to those on a standard diet." (PMID 39456701, 2024). "Two other causes of fetal hyperthyroidism are TSHR mutations and McCune-Albright syndrome." (PMID 37233673, 2023). "According to the location of mutation sites on the TSHR gene, hypothyroidism or hyperthyroidism may be induced." (PMID 37686882, 2023). "Consequently, the interaction between the TSHR and its specific autoantibody (TRAb) causes an immune response that results in goiter, hyperthyroidism, ophthalmopathy, and dermopathy." (PMID 36980259, 2023). "So, it can be concluded that the TSHR-related rs2268458 polymorphism is associated with hypothyroidism and hyperthyroidism in the male and female populations of Yazd Province, Iran and C allele can be a risk factor for some physio-biochemical and hormonal imbalance in the thyroid disorder patients." (PMID 36130976, 2022). "Furthermore, they propose that GD is a stage prior to HT, where thyroid-stimulating antibodies (TSAbs) (Th1-related IgG1) appear in the early humoral autoimmune response, which immediately activate the TSHR and cause hyperthyroidism (GD)." (PMID 35894054, 2022). "In the recent years, it has been recognized that genetic immunization of TSHR seems to be an effective approach to induce the production of TSHR Antibody in vivo, which is associated with the development of Graves’ -like hyperthyroidism, either by injection of adenovirus or plasmid vectors." (PMID 28319174, 2017). "An association between genotype and phenotype in presence of constitutively active TSHR mutations is difficult to establish since one and the same mutation may lead to variability in the clinical course and onset of hyperthyroidism." (PMID 21274318, 2010).
hyperthyroidism (continued). "To gain further molecular insights into the potential mechanism of TSHR constitutive activity, we tested the cAMP response of these mutations following a stimulation with human chorionic gonadotropin (hCG; 5, 50, 100 IU) as has been reported in some cases of temporary hyperthyroidism." (PMID 38194289, 2024). "Animal models deploying an immunization protocol with thyroid stimulating hormone receptor antibody (TSHR Ab) showed that vitamin D deficiency promoted persistent hyperthyroidism, leading to speculate on a potential modulatory effect of vitamin D on thyroid function." (PMID 32192175, 2020). "Mutations in TSHR may lead to several thyroid diseases, most commonly hyperthyroidism." (PMID 28117293, 2017). "The TSHR group exhibited elevated levels of all three cytokines compared to the normal control group, indicating immune dysregulation typical of hyperthyroidism." (PMID 41010493, 2025). "The pathogenesis of GD involves persistent activation of thyroid-stimulating hormone receptor (TSHR) on thyroid follicular cells by TSHR-Ab, leading to hyperthyroidism and often thyroid enlargement, clinically manifested as a goitre." (PMID 41153638, 2025). "Elevated levels of thyroid-stimulating hormone receptor antibodies (TRAbs) lead to hyperthyroidism and diffuse goiter." (PMID 39944438, 2025). "He presented with severe proptosis, extraocular muscle enlargement, hyperthyroidism, and significantly increased thyroid-stimulating hormone receptor autoantibodies (TRAb)." (PMID 41226056, 2025). "Current American Thyroid Association (ATA) guidelines for diagnosis and management of hyperthyroidism recommend testing for thyroid-stimulating hormone receptor (TSHR) antibodies (TRAbs) to help determine disease etiology." (PMID 40482060, 2025). "Our patient was diagnosed with GD after comprehensive testing revealed hyperthyroidism and positive TSHR-Ab, findings that coincided with the initiation of dupilumab therapy." (PMID 40895907, 2025). "Adoptive transfer of TSHR knockout mouse splenocytes into nude mice induced anti-TSHR autoantibodies, leading to transient hyperthyroidism, followed by hypothyroidism." (PMID 40605078, 2025). "Based on the mice model, our study demonstrates that B. fragilis and its metabolite, propionate, effectively ameliorate hyperthyroidism in GD mice, reduce inflammatory responses and TSHR autoimmunity, and promote immune homeostasis." (PMID 40265938, 2025). "After 15 to 18 months of ATD therapy, hyperthyroidism is generally resolved, and TSHR-Ab levels become undetectable." (PMID 39940745, 2025). "In contrast, the TSHR-induced hyperthyroidism group showed significant thyroid inflammation characterized by increased lymphocytic infiltration, follicular disruption, and signs of thyrocyte hypertrophy." (PMID 41010493, 2025). "GD is an autoimmune disorder characterized by the presence of stimulating autoantibodies targeting the thyroid-stimulating hormone receptor (TSHR), leading to hyperthyroidism." (PMID 41384633, 2025). "It is caused by thyroid-stimulating autoantibodies that mimic the action of thyroid-stimulating hormone (TSH) by binding to the TSH receptor (TSHR), leading to hyperthyroidism." (PMID 40895907, 2025). "Typically, these TSHR CAMs lead to ligand-independent TSHR activity, an increase in thyroid hormone synthesis, and hyperthyroidism, which is usually persistent and requires ablative therapy in order for patients to avoid relapse." (PMID 38194289, 2024). "GD is recognized as the primary career of hyperthyroidism, with its pathogenesis predominantly involving the activation of immunoglobulin G subclass antibodies against the thyroid-stimulating hormone receptor (TRAb)." (PMID 39872521, 2024). "The changes in thyroid weight, body weight, and tail length during the 8-week treatment were clearly associated with the development of hyperthyroidism (low serum TSH, high T4), most notable in homozygous TSHR M453T females in sufficient-iodine group." (PMID 38194289, 2024).